HMOX1 (heme oxygenase 1)
Diseases named in the same sentence as HMOX1 in open-access papers (continued):
Sharing a sentence is not in itself a finding about the gene and the disease.
infection (continued). "S6, D to F), in contrast to other anti-inflammatory genes including Hmox1, Socs1, and Socs3, which were consistently increased in the expression near sites of infection." (PMID 39813329, 2025). "The role of Hmox-1 and its degradation products is known to have strong implications on the ability to control infections and mitigate their pathological consequences." (PMID 39611159, 2024). "The mRNA transcription level of antioxidant downstream genes heme oxygenase 1 (HO-1) decreased (p < 0.05) after DK/212 infection." (PMID 38542289, 2024). "All drugs activated NRF2, as illustrated 36 h post-infection (hpi), by the increased mRNA level of HMOX1, a known NRF2 target gene." (PMID 39334742, 2024). "infection is still poorly defined despite the fact that the increased expression of Nrf2-regulated genes like Hmox1 suggests that Nrf2 is likely activated following infection with L. donovani, L. chagasi, or L. braziliensis." (PMID 39595091, 2024). "Heme Oxygenase 1 (HO-1) activity controls parasite replication, and the expression is particularly diminished in EVT, which is also more susceptible to infection than CTB." (PMID 36968102, 2023). "Previous studies have shown that Hmox1 has a role in S. Typhimurium clearance after 72 h of infection." (PMID 35739937, 2022). "In a multivariate model testing influence of both status and day on these transcripts, holding day constant revealed a significant impact of infection was retained for Nrf2, Sod1, Sod2, Cat and Hmox1 (p ≤ 0.04)." (PMID 35312688, 2022). "Changes in expression levels of three different transcripts regulated during infection by L. donovani amastigotes (Ccl5), promastigotes (Cd274) or both (Hmox1) was confirmed by RT-qPCR experiments." (PMID 35430587, 2022). "As an inducible defense system against oxidative stress, NRF2/HMOX1 basal expression is relatively low but can be markedly upregulated in response to various stimuli, such as hypoxia, cytokines, LPS, ROS, and infection." (PMID 35732914, 2022). "The results showed that SARS-CoV-2 markedly decreased the protein expression of HMOX1, particularly at 48 h post-infection." (PMID 35732914, 2022). "There was a significant interaction between diet and infection for the antioxidant genes Hmox1 and Keap1, with PTS-PTSO inducing expression in infected mice that was significantly higher than for the other groups." (PMID 36290756, 2022). "To further evaluate the beneficial effect of Hmox1 in bacterial persistence, we treated mice after the beginning of the infection using the drug as a post-disease treatment." (PMID 35739937, 2022). "The authors observed that antioxidant mechanisms mediated by NRF2 and Heme Oxygenase 1 (HO-1) were able to reduce parasite burst in macrophage, indicating that oxidative stress-mediated by infection facilitates parasite survival in host cell environment." (PMID 33826673, 2021). "The infection led to a significant increase in the expression of heme-oxygenase-1 (Hmox), as observed in previous studies, independently of the genotype." (PMID 35008695, 2021). "We also compared expression of NRF2-target genes, Hmox1 and Nqo1, in WT and Tlr3-/- cells at 8 hrs post-infection." (PMID 33765083, 2021). "Numerous models of infection, sterile inflammation, and transplantation have documented the suppressive function of HMOX1 in innate immunity and inflammation." (PMID 34054870, 2021). "While heme oxygenase 1 (Ho1) was low in uninfected macrophages, it was increased upon infection, indicating intracellular oxidative stress." (PMID 34680781, 2021). "In comparison, CCR7 is central for lymphocyte and dendritic cell functioning, including migration to tissues with active infection, and HMOX1 affects immune functions by controlling Heme metabolism." (PMID 33163005, 2020). "(B) Ectopic HMOX1 expression in retina by infection of AAV8 or AAV8-HMOX1 virus was visualized by immunofluorescence (n = 4)." (PMID 32242818, 2020).
infection (continued). "This can be attributed due to the up-regulation of an anti-inflammatory enzyme, HO-1 (heme oxygenase-1) in hepatocytes as observed previously following P. berghei and P. yoelli sporozoites infection." (PMID 32181014, 2020). "In such a context, CoPPIX (through HO-1 increased expression) promotes the progression of infection, and conversely, macrophages from Hmox1−/− mice present lower parasite burden compared to wild-type controls." (PMID 32692767, 2020). "The present data show an increase of the mRNA abundance of heme oxygenase 1 in headkidney in individuals challenged and highlight the increase of the oxidative stress (ROS) in this tissue as a consequence of the IPNv infection." (PMID 29922300, 2018). "The Nrf2 pathway and HMOX1 have been reported to play a role in “tissue tolerance” - the ability of resist pathogen-, inflammation, or oxidative stress-mediated damage during infection or inflammation." (PMID 29269773, 2017). "In this assay, the antioxidant proteins thioredoxin (Trx), peroxiredoxin-6 (PRDX-6) and heme oxygenase-1 (HO-1) were examined at 24, 48 and 72 h post-infection." (PMID 25439655, 2014). "On the other hand, the liver and kidney expression of the membrane iron exporter, Slc40a1 and Hmox1 was significantly higher in Ank1Ity16/Ity16 mice at day 0 and day 2 post infection compared to Ank1+/+." (PMID 23390527, 2013). "The infection of BALB/c mice with P. berghei ANKA, for example, results in a fairly homogeneous 3–4 fold upregulation of HMOX1 mRNA 6 days post infection, comparable to what we observed in uncomplicated cases." (PMID 22438807, 2012). "Infection of HCAEC with the septicemic S. agalactiae strain ATCC® 13813 led to HMOX-1 upregulation, compared to unstimulated cells (2.3-fold after 4 hours, 4.7-fold after 8 hours, and 6.6-fold after 24 hours of infection)." (PMID 21437210, 2011). "Another study of Atlantic salmon (Salmo salar L.)also showed that HMOX1 was down-regulated in spleen to infection with the salmon louse (Lepeophtheirus salmonis) at 22 day post infection." (PMID 20525308, 2010). "Biliveridin reductase a and b (BLVRA and BLVRB) and Heme oxygenase (HMOX1) are involved in degradation of erythrocytes and both Blvra and Blvrb expression increased 2–4 fold in the liver by day 9 post infection." (PMID 19365556, 2009). "Since a previous study suggests that HMOX1 activity is involved in the control of Tg infection in vivo, but the exact mechanisms remain unknown, we explored the possibility of a role of HMOX1 pathway in arbutin-mediated anti-Tg activity in macrophages." (PMID 41379884, 2025). "VSV‐M51 infection resulted in SPP1/HMOX1 downregulation in T98 cells." (PMID 40495644, 2025). "Heme oxygenase-1 (HO-1) is another source of intracellular labile iron and can be highly induced by heme and multiple stressors, including oxidative stress, inflammation, and infection." (PMID 40170719, 2025). "More studies are needed to determine whether other ARE-regulated genes are affected by pUS27, such as Heme Oxygenase-1 (HO-1), which could help the virus mitigate oxidative damage during infection, supporting viral replication and persistence." (PMID 41156604, 2025). "In addition, in macrophages, arbutin not only inhibits infection-induced inflammatory response but also upregulates the expression of heme degrading enzyme heme oxygenase-1, which facilitates biliverdin production." (PMID 41379884, 2025). "This detrimental role for HMOX1 activity in either promoting pathogen replication or impairing the immune response to infection has also been seen in several other bacterial and protozoan pathogens, including Salmonella typhimurium, Brucella, Burkholderia pseuodmallei, and Leishmania chagasi." (PMID 38585264, 2024). "However, the host’s response to this infection involves the detoxification of heme by heme oxygenase-1 (HO-1) into ferrous iron and biliverdin following NRF2 activation, consequently mitigating the oxidative damage caused by malaria infection." (PMID 38660623, 2024).
infection (continued). "However, siRNA-mediated knockdown of Hmox1 during infection increased bacterial release and ferroptotic cell death." (PMID 38585264, 2024). "Moreover, independent of Eimeria infection, Se supplementation elevated (p < 0.05) the heme oxygenase 1 (HMOX-1) expression in jejunal mucosa at 6 days post-infection (dpi)." (PMID 37174598, 2023). "In contrast to that of enriched inflammation- and IFN-related genes, the expression of genes associated with the antioxidative response was widely suppressed by SARS-CoV-2, and among these genes, the expression of HMOX1 was profoundly downregulated at 24 h and 48 h post-infection." (PMID 35732914, 2022). "Although this was not a focus of a study, we did not identify any sex-specific interaction between the HMOX1 promoter repeat and sex, despite the known association between certain infections and biological sex." (PMID 35551540, 2022). "It is also clear that the role of iron, heme, and HMOX1 in human infection is complex." (PMID 35551540, 2022). "Moreover, infection of Vero hTMPRSS2 cells with SARS-CoV-2 decreased levels of Heme Oxygenase 1 (HO-1) and NAD(P)H quinone oxidoreductase 1 (NQO1) induced by Nrf2." (PMID 36009328, 2022). "During infection splenic TRMs highly express Hmox1 gene, coding for Heme oxygenase enzyme." (PMID 36420267, 2022). "We evaluated the effect of pharmacologic modulation of Hmox1 in a mouse model of acute and persistent S. Typhimurium infection by administering the Hmox1 activity inductor cobalt protoporphyrin-IX (CoPP) or inhibitor tin protoporphyrin-IX (SnPP) before infection." (PMID 35739937, 2022). "In addition, viruses, such as hepatitis C virus (HCV) and spring viremia of carp virus (SVCV), specifically downregulate HMOX1 during infection." (PMID 35047922, 2021). "To analyze whether overexpression of HMOX1 might induce Ddit3 expression in the unstressed condition, we examined Ddit3 expression in neural retinas 2 weeks after infection with AAV8-HMOX1." (PMID 33691741, 2021). "Considering that in Lam infection, Hmox1 was implicated in parasite survival, we decided to verify whether HO-1 could play a similar role as NRF2 in LgyLRV1+ infection." (PMID 33765083, 2021). "In sharp contrast, modulation of Hmox1 expression and HO-1 enzymatic activity during experimental liver stage infection revealed that HO-1 is a down-modulator of the inflammatory response against intra-hepatocytic parasite forms and acts to promote liver stage infection." (PMID 31417551, 2019). "Hmox1 mRNA expression progressively increased during infection in both A/J and AcB61 liver." (PMID 28507548, 2017). "Macrophages upregulate heme oxygenase-1 (HMOX1), a heme-degrading enzyme, in response to inflammation or infection; therefore we hypothesized that macrophages dynamically regulate FLVCR in response to inflammation or infection." (PMID 27006955, 2016). "In consequence, upregulated expression of HMOX-1 could reflect a protective mechanism against thrombotic complications after infection with GBS." (PMID 21437210, 2011). "Hence enhancing HMOX1 activity could be an alternative to antagonize heme-induced effects and thereby controlling infection and inflammation." (PMID 30356117, 2018). "Though our study was not designed to test dose response or pre-existing “deficiency” of antioxidants, the impact of BSH on expression of HMOX1 and NQO1 after infection may have been linked to baseline levels, i.e. the lower the starting levels of expression, the greater the impact." (PMID 24910991, 2014). "The convergence of these pathways explains the consistent upregulation of HMOX1 and SAT1 across infection stages." (PMID 40141146, 2025). "Ferroptosis-related genes HMOX1 and SAT1 show stable expression across different infection models and strains, making them promising targets for genetic selection." (PMID 40141146, 2025).
infection (continued). "Quercetin acts on the anti-inflammatory heme oxygenase-1 (HO-1) pathway to inhibit the expressions of TNF-α, IL-1β, IL-6, and NO production in the serum to attenuate inflammation induced by infection." (PMID 38765079, 2024). "Heme oxygenase-1 (HO-1) and nuclear receptor co-activator 4 (NCOA4) involved in converting bound iron into free iron were upregulated after TgCtwh3 infection." (PMID 37651502, 2023). "Reduction in the level and activity of heme oxygenase-1, due to its participation in the reduction of ZIKV replication, promotes successful infection of the host by ZIKV." (PMID 37775774, 2023). "RNA-seq showed that the expression of ACOD1 and its downstream genes (HMOX1, TNFAIP3, TAP1, ATF3, and NRF2) was significantly upregulated post infection." (PMID 37256871, 2023). "Infection modestly raised KEAP1 mRNA expression in WT and XPO1 knock-down cells, but tended to downregulate the other analyzed mRNAs except HMOX1." (PMID 37459366, 2023). "While the upregulation of MRC1 and HMOX1 mRNA after infection was observed previously, we noted a downregulation of MRC1 and HMOX1 protein levels in moMΦ." (PMID 34835004, 2021). "WB data showed that after 2 weeks of infection, AAV8-GFP or AAV8-HMOX1 correspondingly induced high expression of GFP (4.73 ± 1.01fold, n = 3) or HMOX1 (5.26 ± 1.52 fold, n = 3) in both Ddit3+/+ and Ddit3−/− neural retinas." (PMID 33691741, 2021). "It was later found that upon infection, macrophages produce ROS in response to ESAT-6 expressed by Mtb, which drives NRF2 activation of HMOX1 gene transcription." (PMID 33266044, 2020). "It was shown that after infection with ZY05719 and △MetQ respectively, abundances of Pstpip1 and Hmox1 increased, while Src abundance was reduced in the △MetQ treated group, which was in agreement with the LC–MS results." (PMID 33125582, 2020). "Among the tested Fe-responsive genes, expression of HFE1, BMP6, and HMOX1 at 12 weeks, and HAMP at 16 weeks post-infection, was significantly up-regulated." (PMID 31382404, 2019). "A clear difference in expression of iron regulatory genes was observed with a consistent and significant down-regulation of FTH1, SLC11A1, SLC11A2, HMOX1 and TFRC in animals controlling the infection." (PMID 24505407, 2014). "Hmox1 knockout mice succumbed to a low-grade polymicrobial infection that was not lethal in wild-type mice." (PMID 38585264, 2024). "Sod1 and Prdx1 were not significantly affected by infection, while interestingly Hmox1 expression was increased at 2 dpi." (PMID 37022178, 2023). "Sod1, Sod2, Cat, and Nrf2 transcripts were elevated in the E8.5 infection group only, with Hmox1 expression being predicted only by infection but not by infection day." (PMID 35312688, 2022). "In addition, we observed increased steady-state levels of NRF2-regulated antioxidant enzymes, heme oxygenase 1 (HO-1) and glutamate-cysteine ligase catalytic subunit (GCLC), in the presence of nitric oxide compared to vehicle-treated infections." (PMID 33323506, 2020). "After 3 h of infection, Hmox1 mRNA expression levels were not significantly induced in infected neutrophils treated or not with Fe2+." (PMID 29218050, 2017). "Surprisingly, expression of the NRF2-regulated gene HMOX1 was not modulated upon Mabs infection." (PMID 37619220, 2023). "To evaluate whether this phenomenon is also observed during an acute systemic model of infection, we treated C57BL/6J female mice with 5 mg/kg CoPP and the Hmox1 competitive inhibitor tin SnPP, and 24 h later, mice were infected with 1 × 106 CFU of S. Typhimurium." (PMID 35739937, 2022). "Thus, while HMOX1 and FPN1 in macrophages may respond to changes in intracellular heme and iron levels in addition to inflammatory/infectious signals, the primary role of FLVCR in macrophages may be the regulation of heme in response to infection/inflammation." (PMID 27006955, 2016).
cardiovascular diseases (112 papers, 2009 to 2026). "The most studied HMOX1 polymorphism in cardiovascular disease (CVD) is the guanine-thymine dinucleotide repeat polymorphism (GTn)." (PMID 40826355, 2025). "Polymorphisms in the promoter region of heme oxygenase 1 (HO-1) have been linked to the occurrence of cardiovascular disease." (PMID 41020847, 2025). "In addition, a long GTn polymorphism in the promoter of HMOX1, exhibiting low transcriptional activity, is associated with cardiovascular diseases." (PMID 38509740, 2024). "The present study evaluates the capacity of ET-1 to affect endothelin-1-associated hypertrophic activity and decreased expression of heme oxygenase-1 by H9c2 rat cardiomyoblasts in vitro, corresponding to in vivo processes underlying cardiovascular diseases (CVDs)." (PMID 29354880, 2018). "Therefore, several studies have evaluated whether people carrying varying HMOX1 gene polymorphisms have different outcomes with respect to cardiovascular diseases." (PMID 40826355, 2025). "Thus, hmox1a knockout zebrafish could serve as a model resembling human long GTn HMOX1 polymorphism, which leads to lower HMOX1 protein levels and predisposes to cardiovascular disease." (PMID 38509740, 2024). "Defected heme-oxygenase-1 (HO-1) signaling also contributes to decreased antioxidant and anti-inflammatory defense in lung and cardiovascular diseases." (PMID 37371927, 2023). "Of note, numerous studies showed the impact of the constitutive HMOX2 expression, together with HMOX1, in cardiovascular disease." (PMID 36769209, 2023). "Previous studies have widely reported the protective role of Hmox1 in cardiovascular disease, especially in cardiac IRI." (PMID 36091399, 2022). "Heme oxygenase-1 (HO-1), an enzyme that is ubiquitously expressed in all cell types, has been found to take antioxidant effects in many cardiovascular diseases, and its expression is protectively upregulated under DOX treatment." (PMID 33854694, 2021). "The genetic polymorphisms of the HMOX1 gene in humans also indicate the potential importance of HO-1 in the pathogenesis of cardiovascular diseases (CVDs)." (PMID 31344980, 2019). "Upregulation of heme oxygenase-1 (HO-1), a phase II detoxifying enzyme, in endothelial cells is considered to be helpful in cardiovascular disease." (PMID 26132561, 2015). "In cardiovascular disease, heme oxygenase-1 (HO-1) is another beneficial factor, it also plays an important role in anti-inflammation process." (PMID 24817581, 2014). "Induction of heme oxygenase-1 (HO-1), an important endogenous antioxidant enzyme, has been considered as a potential therapeutic strategy for cardiovascular diseases." (PMID 23429283, 2013). "A fundamental cytoprotective effect on cardiovascular diseases is played by heme oxygenase-1 (HO-1) that displays antioxidant, anti-inflammatory, and anti-apoptotic effects." (PMID 23975169, 2013). "Two different polymorphisms in the HMOX1 promoter, a (GT) dinucleotide repeat and the -413A>T (rs2071746) single nucleotide polymorphism (SNP) are thought to be involved in the pathogenesis of cardiovascular disease by modulating the expression of HO-1." (PMID 19389234, 2009). "Irrespective of the unclear functional role there are several reports suggesting a role of the (GT)n repeat in the HMOX1 promoter in cardiovascular disease." (PMID 19389234, 2009). "However, the ferrous iron accumulated from the Hmox1 reaction is an abundant source to trigger ferroptosis in various cardiovascular diseases including DOX-stimulated cardiomyopathy." (PMID 37770231, 2023). "Taken together, it’s easy to see that Hmox1 plays a crucial role in iron metabolism and properly regulates DOX-induced cardiovascular disease, which is consistent with our research that overexpression of Hmox1 significantly canceled the cardioprotective effects of SMY in DOX-treated mice." (PMID 37770231, 2023).